TIMP3 (TIMP metallopeptidase inhibitor 3)
Diseases named in the same sentence as TIMP3 in open-access papers (continued):
Sharing a sentence is not in itself a finding about the gene and the disease.
epidermal disease (1 paper, 2022). A skin disease that involves the epidermis. "Consequently, we evaluated the levels of TIMP3 and ATG9A in UVB exposure-related epidermal diseases, including AK and cSCC." (PMID 35450405, 2022).
Erythema (1 paper, 2020). Redness of the skin, caused by hyperemia of the capillaries in the lower layers of the skin. "Our results suggest that MMP‐9 and TIMP‐3 levels could be predictive of RT toxicity, particularly, of acute effects such as erythema and radiodermitis." (PMID 31568637, 2020).
GEJ adenocarcinomas (1 paper, 2013). "A larger-scale and systematic functional characterization of TIMP3 genetic variants, in relevant tissue types, will likely be necessary to reveal the molecular basis for the association of TIMP3 SNPs with GEJ adenocarcinoma survival." (PMID 23527119, 2013). "We have demonstrated the association of TIMP3 polymorphisms with survival of GEJ adenocarcinomas." (PMID 23527119, 2013). "Regardless of the mechanism, our results suggest that TIMP3 genetic variants should be considered as promising prognostic and predictive factors for GEJ adenocarcinoma, and warrant further study." (PMID 23527119, 2013). "Identification of the differentially bound protein and investigation into its expression and role in GEJ adenocarcinoma may highlight the importance of TIMP3 and this SNP in this cancer." (PMID 23527119, 2013).
glomerulosclerosis (1 paper, 2021). A hardening of the kidney glomerulus caused by scarring of the blood vessels. "TIMP3 overexpression in the kidney of MacT3 diabetic mice was also associated with conserved podocyte‐specific markers, suggesting a protective role of TIMP3 in diabetic podocytopathy, a critical player in the pathogenesis of glomerulosclerosis and proteinuria." (PMID 33634991, 2021).
Hyperkeratosis (1 paper, 2022). Hyperkeratosis is a histopathological term defining a thickened stratum corneum and may be present in many different skin conditions, with many possible overlaps. "The G allele of rs2234921 of the TIMP3 gene was only marginally associated with a hyperkeratosis risk (p = 0.06)." (PMID 36499314, 2022).
hypertensive nephropathy (1 paper, 2021). Kidney damage that results from chronically elevated blood pressure; complications include glomerular damage resulting in proteinuria and hematuria. "Another study using a rat model of hypertensive nephropathy observed that the inhibition of TIMP3 was accompanied by a decrease in autophagy markers." (PMID 34599146, 2021).
in situ carcinoma (1 paper, 2006). A malignant epithelial neoplasm which is confined to the epithelial layer without evidence of further tissue invasion. "In the cases where in situ carcinoma or normal epithelium were present, they demonstrated an intense immunopositivity for TIMP-3." (PMID 17032447, 2006). "TIMP-3 protein was immunodetected in the cytoplasm of the malignant cells and the peritumoral stroma, as well as in in situ carcinoma and normal epithelium." (PMID 17032447, 2006).
infertile (1 paper, 2009). "For example, three possible target genes for down-regulated miRNAs, TIMP3, SOX9 and GADD45G, were significantly increased in infertile testis." (PMID 19210773, 2009).
Interstitial cardiac fibrosis (1 paper, 2022). A type of myocardial fibrosis characterized by excessive diffuse collagen accumulation concentrated in interstitial spaces. "Previous studies demonstrate that loss of Timp3 accelerates reactive interstitial cardiac fibrosis likely through lysyl hydroxylase 1-mediated hydroxylation and stabilization of collagens." (PMID 36103570, 2022).
intracranial aneurysm (1 paper, 2015). "In total, there are five MS genes related to intracranial aneurysm (CASP3, ENG, TIMP1, TIMP2, and TIMP3)." (PMID 26486520, 2015).
Kawasaki disease (1 paper, 2025). A rare inflammatory disease characterized by an acute febrile, systemic, self-limiting, medium-vessel vasculitis primarily affecting children. "Regarding cardiovascular diseases, it has been reported that miR-197-3p induces damage in human coronary arterial endothelial cells by regulating target genes such as TIMP3 and IGF1R, especially in Kawasaki disease." (PMID 41009512, 2025).
keloid (1 paper, 2007). An irregularly shaped, elevated mark on the skin caused by deposits of excessive amounts of collagen during wound healing. "A lower expression of MMP-28 and elevated expression of TIMP-3 in leiomyomas compared to keloids imply a lower matrix turnover with an increase angiogenic and pro-apoptotic activities that has been associated with TIMP-3." (PMID 17718906, 2007).
Lassa fever (1 paper, 2021). A viral hemorrhagic fever that is caused by the Lassa virus, which is transmitted by contact with infected rodents; it is characterized by fever, headache, malaise, myalgia, and hearing loss. "Genes involved in extracellular matrix and cell-adhesion were also modulated, particularly during fatal Lassa fever (NID1, TIMP3, ITGA11, TGM2, MMP8/9, OLFM4, PCDH20, and CADM3), as well as some others involved in coagulation (SERPIN, TFPI2) and apoptosis (CLU, BCL2L14)." (PMID 33398113, 2021).
late-onset retinal degeneration (1 paper, 2025). Late-onset retinal degeneration is an inherited retinal dystrophy characterized by delayed dark adaptation and nyctalopia and drusen deposits presenting in adulthood, followed by cone and rod degeneration that presents in the sixth decade of life, which leads to central vision loss. "These include Sorsby’s dystrophy (TIMP3 mutation), Doyne Honeycomb dystrophy (EFEMP1 mutation), and Late-Onset Retinal Degeneration (L-ORD, C1qTNF5 mutation)." (PMID 39983974, 2025).
liver failure (1 paper, 2021). A liver disease characterized by the liver losing or has lost all of its function. "Furthermore, aberrant ADAM10 activity in TIMP-3 deficient mice promoted liver failure in a model of hepatic ischemia/reperfusion injury." (PMID 33673623, 2021).
lymphadenitis (1 paper, 2019). Acute or chronic inflammation of one or more lymph nodes. "TIMP3 was expressed at significantly higher levels in NS cHL fibroblasts when compared to lymphadenitis fibroblasts (19-fold, Mann–Whitney test, p = 0.002)." (PMID 31671543, 2019). "When all cHL fibroblasts (NS cHL and MC cHL fibroblasts) were compared with lymphadenitis fibroblasts, TIMP3 and MYOCD were most strongly and significantly upregulated (4.2- and 3.9-fold, respectively, filter criteria p < 0.05 and FDR < 0.3)." (PMID 31671543, 2019).
male infertility (1 paper, 2018). The inability of the male to effect fertilization of an ovum after a specified period of unprotected intercourse. "Gossypol-induced male infertility markedly and significantly increased the levels of testicular TBARS, NO, TNF-α, ADAM-17, and interleukins (IL-1β, IL-6, and IL-18) while significantly decreasing the levels of both TIMP-3 and IL-12 compared with those of the control group." (PMID 29849861, 2018).
metastatic tumors (1 paper, 2024). "Notably, we observed a reduction in TIMP3 expression in RCC tissues, especially in metastatic tumors, which was inversely correlated with the metastasis status of RCC." (PMID 39333870, 2024).
mouth neoplasm (1 paper, 2022). "Nonetheless, the methylation of other genes in mouth neoplasm such as APC, DAPK, ECAD, RASSF1, TIMP3 and p16, have retrieved more promising diagnostic and prognostic values." (PMID 35888599, 2022).
myocarditis (1 paper, 2021). Myocarditis is a condition that is characterized by inflammation of the heart muscle (myocardium). "EP4 stimulant may be a promising and novel therapeutic agent that rescues cardiac malfunction during myocarditis and prevents adverse ventricular remodeling after myocarditis by promoting the TIMP-3/MMP-2 axis." (PMID 34702968, 2021).
oligoarticular JIA (1 paper, 2022). "S100A4, TIMP3, and NBL1 are overexpressed in pre-extension oligoarticular JIA FLS compared to polyarticular JIA FLS." (PMID 36167601, 2022).
oligodendroglioma (1 paper, 2009). A well-differentiated (WHO grade II), diffusely infiltrating neuroglial tumor, typically located in the cerebral hemispheres. "Other genes hypermethylated in oligodendrogliomas include the tumor suppressors CDKN2A, CDKN2B and RB1, as well as DAPK1 (death-associated protein kinase 1), ESR1 (estrogen receptor 1), THBS (thrombospondin 1) and TIMP3 (tissue inhibitor of metalloproteinase 3)." (PMID 19333441, 2009).
osteosclerosis (1 paper, 2010). Abnormally high bone density. "Finally, over-expression of human TIMP-3 caused a late onset fatal osteosclerosis." (PMID 20941363, 2010).
pancreatic neuroendocrine tumor (1 paper, 2022). Pancreatic endocrine tumor, also known as pancreatic neuroendocrine tumor (PNET), describes a group of endocrine tumors originating in the pancreas that are usually indolent and benign, but may have the potential to be malignant. "Furthermore, MUTYH/CHEK2, BRCA2, CDKN2A, and TIMP3 have also been associated with pancreatic neuroendocrine tumors." (PMID 35163032, 2022).
periodontitis (1 paper, 2025). An acute or chronic inflammatory process that affects the tissues that surround and support the teeth. "Previous studies have reported heterogeneity in gingival fibroblasts in periodontal tissues, with four subsets significantly altered in periodontitis: Fib 1.1 (CXCL1, CXCL2, CXCL13); Fib 1.2 (APCDD1, IGFBP2, MRPS6); Fib 1.3 (APOD, GSN, CFD); and Fib 1.4 (TIMP3, ASPN, COL11A1)." (PMID 40801798, 2025).
pneumonia (1 paper, 2024). An acute, acute and chronic, or chronic inflammation focally or diffusely affecting the lung parenchyma, caused by an infection in one or both of the lungs (by bacteria, viruses, fungi, or mycoplasma.). "GAS5 has a role in pneumonia by regulating the microRNA-222-3p/TIMP3 axis." (PMID 38407972, 2024).
polycystic ovaries (1 paper, 2020). "On the other hand, other studies have shown that the concentration of TIMP-3 mRNA is significantly lower in polycystic ovaries." (PMID 33419373, 2020).
Post-kala-azar dermal leishmaniasis (1 paper, 2018). "Some authors suggest that TIMP-1 and TIMP-3 may contribute to pathology in Post-kala-azar dermal leishmaniasis (PKDL) and may inhibit wound healing." (PMID 30572657, 2018).
renal carcinoma (1 paper, 2021). A carcinoma arising from the epithelium of the renal parenchyma or the renal pelvis. "The viability of TIMP3-overexpressing 786-O renal cancer cells was determined using the CCK-8 assay, which showed that the proliferation of these cells was significantly inhibited." (PMID 34778292, 2021).
retinopathy of prematurity (1 paper, 2017). A bilateral retinopathy characterized by neovascularization, scarring, retinal detachment, and eventually blindness. "Levels of THBS1, MMP8, MMP9, MMP25, TIMP2 and TIMP3 increased as severity of BPD and retinopathy of prematurity (ROP) increased, whereas ETS1, LEF1 and SPOCK2 exhibited the opposite trend." (PMID 28103583, 2017).
sarcopenia (1 paper, 2021). Progressive decline in muscle mass due to aging which results in decreased functional capacity of muscles. "Adipocyte infiltration in skeletal muscle during injury repair deteriorates function and is linked to sarcopenia in humans; this effect is suppressed by blockade of Hedgehog signaling, which restricts adipogenesis via TIMP3 and supports muscle regeneration." (PMID 33731683, 2021).
scleroderma (1 paper, 2013). Scleroderma is a rare autoimmune connective tissue disorder characterized by abnormal hardening of the skin and, sometimes, other organs. "In addition, TIMP-3 expression is induced in fibroblasts in scleroderma skin, suggesting a role for TIMP-3 in dermal fibrosis." (PMID 23468994, 2013). "TIMP-3 gene expression is also upregulated in human scleroderma fibroblasts, and it is further enhanced by TGF-β, suggesting that TIMP-3 as an ECM component is involved in the pathogenesis of dermal fibrosis." (PMID 23468994, 2013).
spinal cord ischemia (1 paper, 2020). Reduced blood flow to the spinal cord which is supplied by the anterior spinal artery and the paired posterior spinal arteries. "Moreover, miR-136 has been reported to improve neurocyte apoptosis associated by spinal cord ischemia injury by mediating changes in TIMP3 expression." (PMID 33109253, 2020).
Ureteral obstruction (1 paper, 2021). Obstruction of the flow of urine through the ureter. "In a mouse model of unilateral ureteral obstruction, mice lacking TIMP-3 exhibited increased renal injury, increased activation of fibroblasts and greater interstitial fibrosis." (PMID 35082694, 2021).
urothelial carcinoma (1 paper, 2024). A malignant neoplasm derived from the transitional epithelium of the urinary tract (urinary bladder, ureter, urethra, or renal pelvis). "Based on the expression of SDC1, LUM, VEGFA, TIMP3 and WNT7B in various urothelial carcinoma cell lines in the CCL database, we selected J82 and UMUC3 as the verification cell lines, and marked them with puromycin resistance labelling." (PMID 38183115, 2024).
uveal melanoma (1 paper, 2015). A melanoma derived from melanocytes of the uveal tract. "Interestingly, a study of uveal melanomas observed high levels of TIMP3 mRNA transcripts in association with little to no expression of TIMP3 protein." (PMID 25587717, 2015).
tumor (356 papers, 2001 to 2025). "TIMP3 has the potential to be a therapeutic target and an indicator of tumor susceptibility to numerous anticancer drugs, in addition to being a biomarker for predicting the development of cancer." (PMID 41009435, 2025). "Low TIMP3 expression is frequently associated with poor prognosis, increased tumor aggressiveness, and metastasis." (PMID 41009435, 2025). "The expression levels of various genes associated with immunity in a variety of tumor types were correlated with TIMP3 expression." (PMID 41009435, 2025). "In conclusion, it was observed that TIMP3, which is a tumor suppressor and a target of miR-181b, caused significant suppression in the liver." (PMID 38372909, 2024). "Clinically, patients with higher levels of TIMP3 mRNA in tumour-associated stromal areas have unfavourable clinical outcomes." (PMID 38542164, 2024). "In conclusion, individuals with UCC are associated with lower level of tumor T status under the presence of TIMP-3 SNP rs9862 variant." (PMID 36860920, 2023). "In conclusions, TIMP-3 SNP rs9862 variant is associated with lower tumor T status of UCC while TIMP-3 SNP rs9619311 variant is correlated to muscle invasive UCC development in non-smoker." (PMID 36860920, 2023). "Expression of MMP -2, 9, 11, and 13, and TIMP-3 phenotypically define ECs associated with future tumor development." (PMID 37108185, 2023). "In our study, the TIMP-3 SNP rs9862 variant is associated with lower tumor T status in patients with UCC." (PMID 36860920, 2023). "Among four TIMPs, TIMP1 overexpression or TIMP3 silencing is considered to be associated with tumor progression." (PMID 35559040, 2022). "Compared with the CC homozygous, the TIMP3 rs9862 CT + TT polymorphic variant was found to be associated with clinically advanced tumor stage (p = 0.030) and Gleason total score upgrade (p = 0.002) in prostate cancer patients." (PMID 36612628, 2022). "In EAC patients, a significant association was found between CDKN2A, MGMT or TIMP3 promoter hypermethylation and tumor location (p = 0.034, p = 0.0070 and p = 0.013, respectively, Fisher’s exact test)." (PMID 35701814, 2022). "Here, by immunohistochemistry and western blotting analysis, we demonstrated overexpression of MMP-8/-13 along with a down-regulation of MMP-1, associated with a decrease in TIMP-3 levels in tumor compared with normal skin samples." (PMID 36713871, 2022). "Reduced protein expression of TIMP-3 was associated with reduced tumor differentiation and increased metastatic activity, since its binding to MMPs in tumor cells is leading to a reduced ECM-degrading activity." (PMID 36713871, 2022). "Gene promoter hypermethylation has been reported as a marker and mechanism of oncogenesis, while TIMP3 promoter methylation has been closely linked with tumor metastasis and invasion." (PMID 33653378, 2021). "Many over-expressed genes in tumor-associated T cells were involved in tissue remodeling (e.g., Col1a1, Col4a1, Fn1, Lamc1, Mmp2, Mmp10, Timp3) and cell motility/adhesion (Rhoc, Itga1, Itgav)." (PMID 31477729, 2019). "A recent study demonstrated that higher TIMP-3 expression was associated in tumor development by regulation of invasion and metastasis." (PMID 29467412, 2018). "We also observed that MMP-2 and TIMP-3 were downregulated after the knockdown of PANDAR, and MMP-2 and TIMP-3 have been implicated in the regulation of the metabolism of the extracellular matrix, tumor progression and metastasis." (PMID 28545465, 2017). "Likely, Timp3 stromal deficiency stalls tumor progression at an early stage in PyMT Timp3−⁄− mice resulting in the large differences observed compare to PyMT Timp3+/+ at 60 days of age." (PMID 25807548, 2015). "The study of Timp3 expression in human tumor samples has led to the general conclusion that its loss is correlated with advanced tumor stage and even nodal involvement." (PMID 25807548, 2015).